VIM (vimentin)
Diseases named in the same sentence as VIM in open-access papers (continued):
Sharing a sentence is not in itself a finding about the gene and the disease.
glioblastoma (89 papers, 2009 to 2025). The most malignant astrocytic tumor (WHO grade IV). "Comparing 1464 EMT-associated genes in glioblastoma with the pan-cancer dataset, we uncovered three key genes: VIM, EMP3, and AHNAK." (PMID 38229014, 2024). "In another study, high expression of vimentin in glioblastoma patients was associated with poor progression-free survival, and withaferin A inhibited glioblastoma cell migration and invasion activity." (PMID 37259311, 2023). "Higher expression of VIM was attributed to the progression of glioblastoma and was linked to a reduced survival rate." (PMID 35571016, 2022). "For example, the combination of GFAP, EMA, S-100 and vimentin was used to assist epithelioid glioblastoma (Ep-GBM) which is one provisional new variant of glioblastoma added to the WHO 2016 classification." (PMID 31968004, 2020). "In glioblastoma cells, vimentin (VIM) was shown to promote ERK phosphorylation, leading to the activation of NF-κB-regulated genes and NRLP3 inflammasome activation." (PMID 40284705, 2025). "To further elucidate the association between LDH subunits and glioblastoma (GBM) phenotypes, we analyzed the expression of OLIG2 (a marker for the proneural phenotype) and VIM (a marker for the mesenchymal phenotype)." (PMID 39895794, 2025). "Our findings demonstrated that valproate treatment in glioblastoma T98G cells effectively reduced the mRNA levels of vimentin, alpha-SMA, and twist, while simultaneously increasing the expression of the epithelial protein E-cadherin." (PMID 40724848, 2025). "Antibodies that bind to cell-surface VIM have been effectively used to detect CTCs in patients with gastric cancer, sarcoma, glioblastoma, neuroblastoma, hepatocellular carcinoma, breast cancer, prostate cancer, and lung cancer." (PMID 39766058, 2024). "Glioblastoma also exhibits positivity for glial fibrillary acid protein, vimentin, and S100, with varying Ki-67 indices." (PMID 39803131, 2024). "Regarding the mechanism of action for anti-cell-surface VIM therapies, it appears that CSCs have more cell-surface VIM expression, as most cell-surface VIM-expressing cells also expressed the glioblastoma CSC markers, CD133 or CD44." (PMID 39766058, 2024). "In our research, we investigated the effect of anti-vimentin nanobody Nb79 on glioblastoma cell invasion." (PMID 36765531, 2023). "Recent studies have found that glioblastoma cells expressing vimentin have strong proliferative ability in vitro." (PMID 36633681, 2023). "The anti-vimentin nanobody Nb79 significantly reduced the invasion of the differentiated glioblastoma cell line U-87 MG and the glioblastoma stem cell line NCH421k, with greater effect in NCH421k compared with U-87 MG cells." (PMID 36765531, 2023). "In conclusion, our results suggest that anti-vimentin nanobody is a promising tool to target glioblastoma cell invasion." (PMID 36765531, 2023). "In summary, this is the first study to demonstrate that anti-vimentin nanobody reduces the invasion of glioblastoma cells, particularly GSCs that are resistant to existing therapies and are responsible for tumour recurrence." (PMID 36765531, 2023). "The expression of VIM was also analysed on cellular level in glioblastoma stem cells (GSCs), glioblastoma cells (GBM cells) and normal human astrocytes." (PMID 36765531, 2023). "The aim of this research was to examine the effect of the anti-vimentin nanobody Nb79 on the invasion of a glioblastoma differentiated cell line as well as glioblastoma stem cell (GSC) line in vitro as well as in vivo in zebrafish embryos." (PMID 36765531, 2023). "In U251 glioblastoma-derived cell line interaction between VIM and GSK3β was demonstrated with implications in cell migration; HeberFERON modified phosphorylation on both proteins." (PMID 36552831, 2022). "Another study also reported that bLF treatment decreased expression of snail and vimentin but increased that of cadherin in a glioblastoma cell line." (PMID 36199689, 2022).
glioblastoma (continued). "The study evaluated two significantly upregulated genes, SPARC (secreted protein acidic and rich in cysteine) and VIM (vimentin) for glioblastoma." (PMID 35571016, 2022). "In this study, we interrogate the role of vimentin controlling EV71-induced inflammasome generation in vimentin-knockdown (VIM-KD) and Vimentin-wildtype (VIM-WT) glioblastoma cell models (U251 cells) to disclose the holistic crosstalk between EV71 and host." (PMID 35807435, 2022). "In the studies, EV71 infection, ERK1/2 phosphorylation, and activation of NLRP3 are abolished in glioblastoma cells with low vimentin expression by CRISPR/Cas9-mediated knockdown." (PMID 35807435, 2022). "U87 cells were marked using vimentin, as it is expressed in glioblastoma cells when the tumor presents stemness characteristics and can be differentiated from CAFs due to being negative for ER-TR7." (PMID 36376978, 2022). "It is putative that EV71 and its virus proteins are in touch with vimentin protein located on the surface of brain glioblastoma cells during the infection process, as seen in the proposed schematic paradigm." (PMID 35807435, 2022). "In this study, HOXA-AS2 was found to be overexpressed in glioblastoma tissues and cells, to inhibit cell apoptosis, and to enhance cell proliferation, migration, invasion and the protein expression of Twist, Slug, Vimentin and MMP-2." (PMID 33430870, 2021). "By targeting glioblastoma multiforme cells using an antibody against cell-surface vimentin (defined as the CSV antibody; clone 84-1), surface vimentin is internalized, which results in cell apoptosis and inhibition of tumor growth." (PMID 34299089, 2021). "The distribution of vimentin, a marker of glioblastoma, also changed in cells treated with GS extract, with a distribution pattern similar to α-tubulin." (PMID 34571747, 2021). "Immunofluorescence also demonstrated the same change of Vimentin between control and shNOX4 glioblastoma cells after treatment with TGF-β1 for 24 hours." (PMID 34257808, 2021). "In a similar manner to P15, the monoclonal antibody 86C bound to cell surface vimentin and specifically targeted glioblastoma cells." (PMID 31940801, 2020). "Vimentin staining for glioblastoma cells revealed an overall decreased invasion upon STAT3 knockout, as to be expected from our previous findings." (PMID 32967361, 2020). "86C binding led to the endocytosis of vimentin, caspase-3 activation, and apoptosis induction in multiple glioblastoma cell lines." (PMID 31940801, 2020). "Both miRNAs, miR-124-3p and miR-138-5p, target VIM gene, which was overexpressed in the U251 and U87 glioblastoma cell lines-derived sEVs." (PMID 33187334, 2020). "In order to find out by which mechanism the proteins Robo1 and Slit2 regulate radiation-induced motility of glioblastoma cells, we investigated the expression of the migration-associated proteins fascin and FAK/pFAKY925 and the EMT marker protein vimentin." (PMID 29864155, 2018). "Sumoylation of vimentin in the nucleus regulates the structure and motility of glioblastoma multiforme cells." (PMID 28670517, 2017). "Three human genes, CD74, CXCR4, and VIM, were common to both the glioblastoma and lymphoma transplants." (PMID 25259521, 2014). "Bcl-w promotes the mesenchymal traits of glioblastoma cells by inducing vimentin expression via activation of transcription factors, β-catenin, Twist1 and Snail in glioblastoma U251 cells." (PMID 23826359, 2013). "Initially, we examined the expression levels of mesenchymal markers (vimentin, Twist1, Snail and Slug) in U251 glioblastoma cells via overexpression or depletion of Bcl-w with RNA interference." (PMID 23826359, 2013).
glioblastoma (continued). "Vimentin was found to be detectable in astrocytomas and glioblastomas (grade IV astrocytomas), meningiomas, and ependymomas but not in oligodendrogliomas and medulloblastomas." (PMID 20169076, 2010). "In our experiments, Numb5 and Numb6 showed interactions with Cdc42, IQGAP1 and vimentin, a protein expressed in radial glial and glioblastoma cells." (PMID 21122105, 2010). "Furthermore, TSPAN6 elicited the progress of EMT via downregulation of N-cadherin and upregulation of E-cadherin and Vimentin in glioblastoma cells." (PMID 38725860, 2024). "However, in U87 glioblastoma cells, 6HLN mainly exhibited cancer-stimulatory effects by increasing cell viability, enhancing migratory properties supported by vimentin overexpression, and upregulating the expression of the IL1β proinflammatory protein." (PMID 39683752, 2024). "Vimentin was expressed in all glioblastoma cell lines analyzed in this study." (PMID 35701472, 2022). "In our study, we found that TGF-β could increase the expression of CTSS in glioblastoma and, meantime, induce expression levels of mesenchymal proteins (N-cadherin, Vimentin), and decrease E-cadherin level in glioblastoma." (PMID 33613746, 2021). "We also observed that TGF-β could change the morphology of glioblastoma cells, redistribute intermediate-filament, vimentin, which was highly relevant to mesenchymal type cells and enhanced mobility." (PMID 33613746, 2021). "The expression of this gene was inversely associated with the expression of miR-124-3p and miR-138-5p, suggesting a malignant role of the VIM gene that could be further investigated as a potential glioblastoma biomarker in small extracellular vesicles." (PMID 33187334, 2020). "The VIM gene was significantly overexpressed in the sEVs of the U251 and U87 glioblastoma cell lines, while VIM-targeting miR-124-3p showed an inverse expression compared to VIM itself, as it was downregulated in the sEVs of U251 and U87 compared to the NCH644 stem cell line." (PMID 33187334, 2020). "Interestingly O1 (oligodendrocyte marker) and vimentin (astrocyte marker) were also expressed in glioblastoma tumor cells (respectively)." (PMID 30723234, 2019). "Moreover, in our model, down-regulation of vimentin, Snail and Slug was observed upon autophagy induction, consistent with the results of a previous study on glioblastoma cells." (PMID 29538296, 2018). "To test the hypothesis that hypoxia induces mesenchymal change in glioblastoma, we evaluated the expression of the mesenchymal marker vimentin using immunofluorescence under various oxygen concentrations at 24 or 48 hours." (PMID 25957416, 2015). "Vimentin knockdown additionally inhibited invasion of U251 glioblastomas." (PMID 23826359, 2013). "Our phosphoproteome data also indicated that some marker molecules for glioblastoma initiating cells, such as nestin and vimentin, were found to be highly phosphorylated with many novel phosphorylation sites in addition to previously reported ones on these key molecules." (PMID 22912867, 2012). "Notably, genes such as SPARC and VIM are upregulated in glioblastoma samples." (PMID 38840833, 2024). "This study found that N-cadherin, vimentin, and Twist were downregulated in all three glioblastoma cell lines (U87MG, LNZ308, and LN229) with the increase in the metformin dose, indicating that metformin could reduce glioblastoma migration and invasion by inhibiting EMT." (PMID 35897747, 2022). "In addition, vimentin has been confirmed as a target gene of miR-378 in glioblastoma Cells." (PMID 24555885, 2014). "For instance, TTFields combined with RT effectively suppress cell migration and invasion in glioblastoma multiforme (GBM) cells by inhibiting proteins such as MMP-9 and vimentin." (PMID 39881333, 2025).
glioblastoma (continued). "In this context, using glioblastoma models, P2X7 activation has been related to the acquisition of EMT markers in mRNA (CDH2, SNAIL, Zeb1) and proteins (N-cadherin, ZEB1, vimentin, and TWIST), as well as the promotion of spheroid formation." (PMID 37966629, 2025). "CAFs in glioblastoma are characterized by expression of α-SMA, COL1A1, FAP, TNC, PDGFR-α, PDGFR-β, PDPN, VIM (vimentin), LOX, CAV1 and S100A4." (PMID 40136652, 2025). "Both mesenchymal markers VIM and SNAIL expression levels were normalized to U87 human glioblastoma cell line, which is known to express mesenchymal markers." (PMID 40654246, 2025). "In terms of downregulated genes in glioblastoma, we found NDRG4, SERPINA3, RPN2, VIM, and TIMP1 to be differentially the most downregulated genes." (PMID 38769480, 2024). "Furthermore, to investigate whether Sortilin also transduces the anti-MT function of Presenilin1 in glioblastoma cells, we employed western blotting assays to detect Vimentin, N-cadherin, and MMP2 expression when cells were lost or gained function of Presenilin1 and/or Sortilin." (PMID 34781973, 2021). "To further analyze the relationship between TGF-β and E-cadherin, N-cadherin, and vimentin, the marker proteins of EMT, we selected 16 cases of glioblastoma with the highest and lowest expression levels of MICAL2 in the TCGA database, respectively." (PMID 34868922, 2021). "In glioblastoma multiforme cells, PD-L1 activates the EMT process by upregulating Slug, β-catenin and Vimentin and by downregulating E-cadherin, via activation of the RAS/MEK/ERK signaling." (PMID 33363153, 2020). "Glioblastoma cells forming aggregates, as well as undifferentiated GFAP+NNP, co-expressed SOX-2, Nestin, Beta III-tubulin, MAP2, GFAP, Vimentin, Fibronectin and CD44, when cultured under serum-starvation media." (PMID 19216795, 2009). "In our culture model, a population of glioblastoma cells was able to form aggregates composed of cells with multilineage phenotype, i.e. showing expression of: CD44, Vimentin, GFAP, Nestin, Beta III-tubulin, MAP2, Fibronectin and SOX-2, but not CD133." (PMID 19216795, 2009). "Low-grade astrocytomas and oligodendrogliomas tend to exhibit weak or absent vimentin staining, whereas glioblastomas consistently show strong and widespread vimentin positivity." (PMID 40937216, 2025). "While low-grade astrocytomas (grades 2 and 3) may show focal or weak vimentin staining, high-grade astrocytomas and glioblastomas (GBM, WHO grade 4) frequently exhibit strong and diffuse vimentin expression." (PMID 40937216, 2025). "Vimentin positive staining,25higher tumor grade,34, 35, 37and glioblastoma phenotype33were found to be significant negative prognostic factors of OS and PFS." (PMID 37619597, 2024). "Other immunohistochemistry markers usually considered and analyzed for glioblastoma are Glial Fibrillary Axonal Protein (GFAP), S-100, vimentin, oligodendrocyte transcription factor 2 (Olig2) and ATRX, with some finding at least one positive marker in more than 90% of glioblastomas." (PMID 39518074, 2024). "To assess whether the effect of TPPP3 on glioblastoma motility is related to EMT, we examined the expression of EMT-related markers (Vimentin, N-cadherin, e-cadherin)." (PMID 37863960, 2023). "Furthermore, vimentin promotes ERK phosphorylation, leading to NF-κB downstream event and NRLP3 inflammasome activation in glioblastoma cells upon EV71 insult." (PMID 35807435, 2022). "Similar markers of human glioblastoma cells were also expressed as confirmed by comparable expression of specific proteins of human glioblastoma such as vimentin and nestin (data not shown)." (PMID 29156770, 2017). "In the present study, we found that COE treatment increased E-cadherin expression and decreased N-cadherin and vimentin expression, indicating that COE may inhibit the process of EMT and the invasion and migration of glioblastoma cells." (PMID 27716341, 2016).
glioblastoma (continued). "In glioblastoma cell lines, there is homogenous information showing that adenosine receptors A1, A2A, A2B, and A3 are overexpressed in spheroids and are correlated with stemness markers (CD133), EMT markers (vimentin, SNAIL, TWIST, and CDH1), and pharmacological antagonism." (PMID 37966629, 2025). "However, there were no statistical differences in vimentin expression between glioblastoma differentiated cells, GSCs and astrocytes." (PMID 36765531, 2023). "However, in the survival analysis of high-grade glioblastoma (n = 142, data not shown), the interaction between NgR and vimentin had no clinical significance." (PMID 31649250, 2019). "Interestingly, in the contralateral hemisphere no vimentin+ cells were detected either after peptide R or Plerixafor treatment, suggesting that both CXCR4 antagonists could abrogate dissemination of glioblastoma cells at distant cerebral sites." (PMID 27015814, 2016).